BMI1 (BMI1 proto-oncogene, polycomb ring finger)
Diseases named in the same sentence as BMI1 in open-access papers (continued):
Sharing a sentence is not in itself a finding about the gene and the disease.
tumor (continued). "By employing microarray, ChIP, immunoblot and Luciferase reporter assays, we identified a unique mechanism through which BMI1 rescues tumor cells from chemotherapy." (PMID 23671559, 2013). "Conversely, BMI1-overexpressing CaP cells formed increased number of colonies suggesting that BMI1 confers proliferative attributes to tumor cells (Figure 1Fi–Fii)." (PMID 23671559, 2013). "Although several studies demonstrate that BMI1 rescues tumor cells from apoptosis, the concrete mechanism of action is yet to be known." (PMID 23671559, 2013). "Under in vivo conditions, the significance between BMI1-positive, BMI-silenced and BMI1-overexpressed tumor cells vis-à-vis docetaxel therapy was significant." (PMID 23671559, 2013). "Since our data showing a regulatory role of BMI1 on TCF-transcriptional activity in tumor cells is novel, we asked if this phenomenon is limited to CaP cells." (PMID 23671559, 2013). "Initially, we compared the expression of VEGF, NRP2 and BMI-1 in MMTV-GLI1 tumours with MMTV-PyMT tumours and observed dramatically higher expression of these molecules in the MMTV-GLI1 tumours." (PMID 23436775, 2013). "We next asked if the pro-growth role of BMI1 is due to its effect on the proliferative potential of tumor cells." (PMID 23671559, 2013). "MRNA levels of two tumor suppressor genes, p16 and p21, were significantly increased (p<0.01), whereas the expression of two tumor promoting genes, BMI1 and c-MYC, were dramatically decreased (p<0.01) in response to GE treatment." (PMID 23342141, 2013). "Knocking down Bmi-1 induces cell-cycle arrest and rescues the mRNA levels of tumor-suppressive p16INK4ahomeobox A9 (HOXA9) and homeobox C13 (HOXC13) genes." (PMID 22967049, 2012). "Among 78 ESCC patients, 24 patients (30.8%) showed BMI1 positivity, mainly localised in the nuclei of tumour cells." (PMID 23046527, 2012). "By combining the AKT/Ras tumor model and Bmi1 null mice, we investigated the role of Bmi1 during hepatocarcinogenesis induced by AKT/Ras overexpression." (PMID 23029524, 2012). "Our results show that ablation of Bmi1 dramatically decreases the tumor progression in AKT/Ras mice." (PMID 23029524, 2012). "Bmi-1 was highly expressed in the GBM tumor cells we cultured from our case, consistent with a previous report." (PMID 22995409, 2012). "Nuclear expression of BMI (nBMI-1) in tumor cells was detected in 32 of the 64 tumors (50%), cytoplasmic expression of BMI-1 (cBMI-1) was detected in 22 (34.3%), and 10 tumors (15.6%) showed no BMI-1 immunoreactivity." (PMID 23031716, 2012). "As the first step, we evaluated Bmi1 expression in AKT/Ras tumor cells, and we found that expression of Bmi1 in both HCC and CC lesions." (PMID 23029524, 2012). "Recently, the essential role of Bmi1 as an oncogene has been revealed in multiple tumor types, including breast cancer, melanoma, prostate cancer, non-small cell lung carcinomas and HCC." (PMID 23029524, 2012). "Inhibition of Snail1 causes the down-regulation of Nanog, Bmi-1 and CD44, loss of a migration and self-renewal as evidenced by decreased tumor-sphere formation." (PMID 21929801, 2011). "The results of the present study shed light on recent experimental findings related to concentrations of Bmi1 and ubiquitinated histone H2A in stem cells, tumour cells and cells undergoing differentiation." (PMID 22194680, 2011). "Treatment with Bmi-1 siRNA aloneresulted in significant (∼60%) reduction in tumor weight compared tothe control siRNA group." (PMID 21445297, 2011).
tumor (continued). "While cisplatin monotherapy was inactive,combination of Bmi-1 silencing along with cisplatin almost completely abrogatedovarian tumor growth." (PMID 21445297, 2011). "We demonstrated that knockdown of BMI-1 in invasive mesenchymal EC cells significantly reduced in cell proliferation, colony growth and up-regulated the p16 tumor suppressor." (PMID 21851624, 2011). "In our analysis, high Bmi-1 expression showed an obvious correlation with larger tumor size, lymph node involvement, organ metastasis and advanced clinical stage." (PMID 21276221, 2011). "Combination therapy with Bmi-1 siRNA and cisplatinresulted in even greater (∼80%) reduction in tumor weight compared tothe cisplatin only treated group." (PMID 21445297, 2011). "The repression of Bmi-1 not only reduced the volume and weight of the xenografts but also delayed tumor occurrence." (PMID 21276221, 2011). "This family has also been shown to be repressed and to suppress (in specific tumour types) a series of oncogenes that include c-Myb, Bmi-1, BCL-2, WNT3A, and Wip1." (PMID 21629246, 2011). "In contrast to ALDH1− cells, one of three (33.3%) nude mice was detected with the tumor formation after 6-week transplantation of 3000 Bmi-1-overexpressing ALDH1− cells." (PMID 20936121, 2011). "The tumor/normal (T/N) ratio of Bmi-1 message signals varied from approximately 2.5- to 20-fold in eight paired tissue." (PMID 20809956, 2010). "The correlations between anti-Bmi-1 antibodies and tumor stage (P = 0.040), or lymph node status (P < 0.001) were significant." (PMID 20809956, 2010). "Consistent with the upregulated protein level, Bmi-1 mRNA expression was also upregulated in tumor tissue compared with the paired non-tumor tissue as analyzed by real-time PCR." (PMID 20809956, 2010). "This suggested that the Bmi-1 gene plays an important role in cell proliferation and tumor progression." (PMID 20377880, 2010). "A prognostic significance of Bmi-1 was also found in the subgroup of T3~T4 and N1 tumor classification." (PMID 20809956, 2010). "The expression of Bmi-1 was higher in the patients with bigger tumor, deeper invasion, or positive lymph node metastasis." (PMID 21059209, 2010). "We compared the immunoexpressions of Bmi1, c-myc, and Snail with clinical parameters including the degree of histological differentiation, tumour size, TNM classification, depth of invasion, and resection margins." (PMID 20145620, 2010). "We found a significant positive correlation between Bmi-1 overexpression and tumor size, depth of invasion (T classification), or lymph node metastasis (N classification)." (PMID 21059209, 2010). "Our recent study showed that the expression of miR200c in the regional metastatic lymph node of HNSCC tissues was significantly decreased, but Bmi-1 expression was increased as compared to parental tumours (unpublished data)." (PMID 21461395, 2010). "It is described as a potential tumor suppressor in some studies; while in other studies, it was found that similar to BMI1, Mel-18 can act as an oncogene." (PMID 20170541, 2010). "We have previously reported that BMI1 is regulated by another PcG protein Mel-18 in human fibroblasts, and that by doing so Mel-18 can potentially function as a tumor suppressor." (PMID 20170541, 2010). "The mean disease-free time for Bmi-1-negative cases was 53 months (95% CI 29–77 months), whereas patients with tumours with a high frequency of Bmi-1-expressing cells had a mean disease-free time of 112 months (95% CI 97–126 months)." (PMID 20145620, 2010). "Bmi-1 protein expression was detected in 82%, nuclear c-myc expression in 63%, cytoplasmic c-myc expression in 73%, and Snail expression in 100% of all tumours." (PMID 20145620, 2010).
tumor (continued). "Survival analyses for the expression of c-myc, Snail, and Ki-67 were performed in an identical manner as that for Bmi-1, with tumour recurrence as the primary end point." (PMID 20145620, 2010). "It indicates that Bmi-1 antibodies are more prevalent in sera from patients with later stage tumor than in sera from patients with early stage tumor." (PMID 20809956, 2010). "Anti-Bmi-1 was significantly correlated with tumor stage (P = 0.040), and lymph node status (N classification; P < 0.001)." (PMID 20809956, 2010). "In this, the depth of invasion, tumour size, margin of surgical resection, and T classification were included, along with the Bmi-1 protein expression score." (PMID 20145620, 2010). "Consistent with other reports, the anti-Bmi-1 antibody used in our study was tumor cell nucleus staining, but contrast to He's report in which Bmi-1 mainly observed in tumor cell cytoplasm less or not in nucleus." (PMID 20809956, 2010). "It was found that Bmi-1 overexpression was highly correlated with tumor size, clinical stage, lymph node metastasis and T classification." (PMID 21059209, 2010). "Mel-18 regulates cell proliferation and senescence via transcriptional repression of Bmi-1 and c-myc oncoproteins, and is considered to play a dual role, being either oncogenic in some tumor types or acting as a tumor suppressor gene in others." (PMID 21162745, 2010). "It was also discovered that bmi-1 oncogene was up-regulated while ngx6 tumour suppressor gene was down-regulated during the development of tumours." (PMID 20964870, 2010). "In summary, our results and the results of others highlight the role of Bmi1 as a crucial factor for tumor cell expansion and therefore as an attractive target for tumor intervention." (PMID 19156217, 2009). "The overexpression of Bmi-1 protein was correlated with tumor classification, recurrence, clinical stage, and prognosis." (PMID 19228380, 2009). "In line with this we do see reduced tumor cell cycle progression in Bmi1−/−BXB11 tumors and an increase in cells undergoing apoptosis albeit with some delay." (PMID 19156217, 2009). "Nevertheless both models show dependence of tumor expansion on Bmi1 by a mechanism that mainly involves the INK4a/Arf locus." (PMID 19156217, 2009). "Tumor growth was strongly reduced within lungs of Bmi1−/−BXB11 mice in two ways, first there was an approximately two fold decrease of tumor numbers between two weeks and three months of age and second the volume of surviving tumors decreased." (PMID 19156217, 2009). "In conclusion both tumor cell survival and cell proliferation are affected in BXB11 mice with Bmi1 deletion and can account for the observed reduced tumor growth." (PMID 19156217, 2009). "The overexpression of Bmi-1 protein was correlated with tumor classification, recurrence, TNM stage, and prognosis." (PMID 19228380, 2009). "If this were to be the case then K-Ras tumors should be sensitive to the mitogenic cascade blocker CI-1040 that we have previously shown to dramatically decrease tumor burden by differential reduction of Bmi1 positive cells in foci." (PMID 19156217, 2009). "The analysis of the Bmi1−/− SP-C C-RAF BXB mice is hampered by the short life span of these mice that is caused by the deletion of Bmi1 and rarely allowed monitoring of tumor development for more than three months." (PMID 19156217, 2009). "BMI-1 protein expression was significantly weaker in tumours with vascular invasion (P<0.0001), deep myometrial infiltration (P=0.004), and loss of oestrogen receptor (ER) (P<0.0001) and progesterone receptors (PR) (P=0.03)." (PMID 18475299, 2008). "Because we found different expression patterns for EZH2 and BMI1 in the normal mammary gland, it is possible that the expression levels we detected in the tumours are a reflection of BMI1 and EZH2 expression in the cell of origin." (PMID 19099573, 2008).
tumor (continued). "To obtain further insight into the differential associations of BMI1 and EZH2 with overall survival, we analysed the mRNA expression levels of these PcG genes in tumours ranked according to grade." (PMID 19099573, 2008). "Further, this is the first study to relate BMI-1 protein expression to BMI-1 mRNA expression and the level of activation for the previously reported BMI-1 signature in the same tumours." (PMID 18475299, 2008). "BMI-1 expression (Clone F6) was significantly lower in tumours with the presence of vascular invasion (P<0.0001) and deep myometrial infiltration (P=0.004)." (PMID 18475299, 2008). "Proliferative capacity of leukaemic and normal haemopoietic stem cells derived from Bmi-1-/- mice was compromised, suggesting the possible role of Bmi-1 in the maintenance of tumour stem cell phenotype." (PMID 17179983, 2007). "To validate the Bmi-1 expression results, we analyzed the mRNA Bmi-1 expression in a series of 10 mRNA samples from plasma of tumor patients included in the study with a new set of optimized primers." (PMID 17711569, 2007). "Tumours with moderate or strong bmi-1 expression were more likely to have low levels of p16 and p14ARF (P = 0.02)." (PMID 11355949, 2001). "Moreover, BMI1-positive CSCs are slow-cycling, tumor initiating SCs which can give rise to entire regions in OSCCs and are responsible for mediating lymph node metastasis, therapy resistance, and tumor relapse." (PMID 41385756, 2026). "Intriguingly, FOXA1 and BMI1 exhibit opposing roles in modulating the PI3K/Akt pathway: BMI1 activates PI3K/Akt signaling to drive tumor growth and chemoresistance, whereas FOXA1 suppresses MND1 to inhibit progression and enhance oxaliplatin sensitivity via the same pathway." (PMID 40623983, 2025). "Targeting BMI1 offers a promising direction for tumor treatment." (PMID 39744574, 2025). "Our analysis of tumor trajectories already revealed BMI1 itself as a critical node." (PMID 40938978, 2025). "Beyond the repressive effect of Bmi‐1 on the INK4a/ARF tumor suppressor locus, its role might be involved in regulating differentiation pathways to maintain the stem cell niche and influence tumor (stem) cell behavior." (PMID 39791545, 2025). "Interestingly, the inhibition of BMI1 effectively suppressed the self-renewal capacity of CSCs and enhanced their depletion, leading to the suppression of tumor progression." (PMID 41233805, 2025). "In HNSCC, silencing Bmi-1 reduces stemness and tumor formation." (PMID 39866230, 2025). "Similarly, the addition of BMI1 inhibitor to anti-PD-L1 immunotherapy following pre-chemoradiation treatment resulted in synergistic anti-tumor activity in a lung cancer mouse model." (PMID 41233805, 2025). "Interestingly, LW/BW ratios and gross observation showed that Bmi1 overexpression robustly reduces CCA tumor burden." (PMID 40932240, 2025). "By providing a detailed analysis of the molecular mechanisms underlying the deregulation of Bmi‐1 and its clinical implications, this review analyzes Bmi‐1's influence in critical molecular pathways, ultimately promoting tumor growth, stemness, and resistance to treatment." (PMID 39791545, 2025). "Meanwhile, tumor cell-intrinsic BMI1 expression downregulates BMI1 in T cells." (PMID 40034695, 2025). "This study provides new evidence that DHA eradicates CSC characteristics and tumor neovascularization by regulating the miR-200b–BMI-1/VEGF-A/VEGFR2 axis, thereby improving outcomes in patients with platinum-resistant relapse, a major obstacle in the clinical management of OC." (PMID 41345229, 2025).
tumor (continued). "Because Bmi‐1 is essential for tumor cell growth, its downregulation is hypothesized to contribute to the aging of GBM cells and promote their senescence." (PMID 39791545, 2025). "Among them, ENCORI database and tumor samples first suggested the low expression of BMI1 in NPC." (PMID 40087716, 2025). "In addition to the direct effects on the tumor cells, Bmi-1 influences the tumor microenvironment by promoting the activation of the NF-κB and c-Jun N-terminal kinase pathways." (PMID 39866230, 2025). "Because spheroid formation is an indicator of the self-renewal capacity of CSCs, we performed a tumor ball formation assay to further ascertain whether BMI1 can regulate tumorigenic potential." (PMID 40242481, 2025). "Recent advances have identified various biomarkers, such as Ki-67, Cyclin D1, Bmi-1, and EMT-related proteins, that enhance diagnostic accuracy and prognostic assessment, while emerging research into tumor mutational burden and metabolic pathways offers promising therapeutic targets." (PMID 41158948, 2025). "For instance, in the absence of functional INK4a/ARF, Bmi‐1‐deficient cells exhibit reduced differentiation, rapid tumor growth, and a shift toward a less malignant phenotype." (PMID 39791545, 2025). "Furthermore, BMI1 was identified to be the downstream target of miR-362-3p, and BMI1 introduction partially offset the anti-tumor function of miR-362-3p in NPC cells." (PMID 40087716, 2025). "Furthermore, in vivo BMI1 knockdown results in delayed tumor progression, underscoring its importance in tumor maintenance." (PMID 40508013, 2025). "BMI1 promotes the ability of GSCs to self-renew and drives tumor chemo- and radioresistance." (PMID 38918274, 2024). "This interaction between SOX4 and BMI1 contributes to tumor growth and metastasis." (PMID 39349443, 2024). "However, when cells lose the expression of MEG8, SOX9 activity and its downstream target BMI1, proliferation is promoted, bypassing senescence and facilitating tumor formation and progression." (PMID 39706842, 2024). "Down-regulated Bmi-1 inhibited xenograft tumor growth, and RKIP exacerbated this inhibitory effect." (PMID 38914697, 2024). "Moreover, tumor transplantation experiments in nude mice showed that knocking down Bmi-1 inhibited tumor growth in vivo." (PMID 38914697, 2024). "Bmi-1 is related to tumor size, clinical stage and prognosis of gastric cancer." (PMID 38914697, 2024). "Bmi-1 was also over-expressed in tumour compared to tumour margin cells (p < 0.05)." (PMID 39126021, 2024). "Furthermore, evidence suggests that the expression of ALDH1 or BMI1 is affected by the local microenvironment, age, tumor size, and type." (PMID 37686516, 2023). "Depletion of BMI1+ CSCs may thus be an effective strategy for improving anti-PD-1 therapy efficacy and preventing tumor recurrence." (PMID 36810098, 2023). "Several loci that enhance Myc/Pim kinase tumor development have already been identified, including Pal-1/Gfi-1 (Growth Factor Independent 1 Transcriptional Repressor), Bmi-1 (B Lymphoma Mo-MLV Insertion Region 1 Homolog), and Runx2 (RUNX Family Transcription Factor 2)." (PMID 36694243, 2023). "Further, in vitro assays demonstrated that BMI1 knockdown could suppress the SNHG3 activation‐induced tumor promoting effect in BLCa cells." (PMID 36208024, 2023). "In addition, immunohistochemical (IHC) studies showed that GC-7 treatment robustly inhibited the expression of TWIST1 and BMI-1 proteins, which complied with GC-7-mediated downregulation of eIF5Ahpu levels in xenografted tumor tissues." (PMID 37653021, 2023). "SNHG3/c‐MYC/BMI1 axis may be a novel target for regulating tumor growth and metastasis in BLCa patients." (PMID 36208024, 2023). "However, due to off-target effects and quick degradation of the naked Bmi-1-RNAi small RNA oligo by nuclease in body fluids, it is urgently needed to develop a tumor-targeted delivery system with a protective shell." (PMID 38095348, 2023).